MMP13 (matrix metallopeptidase 13)
Description:
Plays a role in the degradation of extracellular matrix proteins including fibrillar collagen, fibronectin, TNC and ACAN. Cleaves triple helical collagens, including type I, type II and type III collagen, but has the highest activity with soluble type II collagen. Can also degrade collagen type IV, type XIV and type X. May also function by activating or degrading key regulatory proteins, such as TGFB1 and CCN2. Plays a role in wound healing, tissue remodeling, cartilage degradation, bone development, bone mineralization and ossification. Required for normal embryonic bone development and ossification. Plays a role in the healing of bone fractures via endochondral ossification. Plays a role in wound healing, probably by a mechanism that involves proteolytic activation of TGFB1 and degradation of CCN2. Plays a role in keratinocyte migration during wound healing. May play a role in cell migration and in tumor cell invasion.
Synonyms: MMP-13; CLG3; MANDP1; MDST
Tractability: Small molecule: an approved drug acts on it; a structure with a bound ligand is known; a high-quality ligand is known; it has a high-quality binding pocket; it belongs to a druggable protein family. Antibody: UniProt places it where antibodies can reach, with high confidence; its Gene Ontology location is reachable by antibodies, with high confidence; UniProt predicts a signal peptide or a membrane-spanning region. PROTAC: a small molecule that binds it is known.
Target class: Metallo protease; Metallo protease M10A subfamily; Metallo protease MAM clan; Protease; Enzyme
Chemical probes: BI-4394 (high quality), ML032, ML033, PD082179, PD083442, T-26c (high quality)
Gene: Protein-coding gene on chromosome 11 (102,942,995 to 102,955,732, reverse strand). Ensembl gene ENSG00000137745.
Subcellular location: Secreted, extracellular space, extracellular matrix; Secreted
Pathways (Reactome):
Extracellular matrix organization: Activation of Matrix Metalloproteinases; Assembly of collagen fibrils and other multimeric structures; Collagen degradation; Degradation of the extracellular matrix
Gene expression (Transcription): RUNX2 regulates genes involved in cell migration
Gene Ontology:
Molecular function: calcium ion binding; collagen binding; endopeptidase activity; metalloendopeptidase activity; zinc ion binding; serine-type endopeptidase activity; metallopeptidase activity; peptidase activity
Biological process: bone morphogenesis; collagen catabolic process; extracellular matrix disassembly; extracellular matrix organization; proteolysis; response to amyloid-beta; bone mineralization; endochondral ossification
Cellular component: extracellular region; extracellular matrix
Genetic constraint (gnomAD): Loss-of-function variants: 36 observed, 44.55 expected, observed/expected ratio (o/e) 0.81, 90% interval 0.62 to 1.07. The upper end of that interval is the gene's LOEUF score, 1.07, which puts it in group 4 of 6, group 1 being the genes least tolerant of losing a copy. Missense variants: 493 observed, 529.62 expected, observed/expected ratio (o/e) 0.93, 90% interval 0.86 to 1. Synonymous variants: 172 observed, 189.52 expected, observed/expected ratio (o/e) 0.91, 90% interval 0.8 to 1.03.
Homologues: Orthologues: macaque MMP13 (99% identical), chimpanzee MMP13 (93% identical), dog MMP13 (92% identical), pig MMP13 (91% identical), rabbit MMP13 (91% identical), guinea pig MMP13 (89% identical), mouse Mmp13 (87% identical), rat Mmp13 (87% identical), tropical clawed frog mmp13l (66% identical), zebrafish mmp30 (45% identical), Caenorhabditis elegans zmp-3 (26% identical), Caenorhabditis elegans zmp-4 (25% identical), and 3 more. Paralogues in human: MMP3 (50% identical), MMP10 (49% identical), MMP8 (49% identical), MMP1 (47% identical), MMP27 (47% identical), MMP2 (46% identical), MMP12 (45% identical), MMP20 (44% identical), MMP9 (39% identical), MMP14 (38% identical), MMP16 (38% identical), MMP24 (38% identical), and 11 more.
Diseases named in the same sentence as MMP13 in open-access papers:
MMP13 is named in the same sentence as 309 diseases in open-access papers, as found by Europe PMC text mining. Sharing a sentence is not in itself a finding about the gene and the disease. The quoted sentences say what the papers report.
osteoarthritis (323 papers, 2005 to 2026). A noninflammatory degenerative joint disease occurring chiefly in older persons, characterized by degeneration of the articular cartilage, hypertrophy of bone at the margins and changes in the synovial membrane. "It has been reported that MMP-13 is induced by pro-inflammatory cytokines, with its increased expression linked to the pathogenesis of diseases such as cancer, osteoarthritis, rheumatoid arthritis, and periodontal disease." (PMID 40332776, 2025). "In joints, zinc transporters are involved in degenerative pathologies; ZIP8 drives osteoarthritis progression by inducing MTF1-dependent MMP-13 expression in chondrocytes, whereas SLC30A6 variants are associated with decreased severity in rheumatoid arthritis." (PMID 41583444, 2025). "Among various MMPs, MMP-1, MMP-3, and MMP-13 are reported to demonstrate increased expression in osteoarthritis and are closely associated with its development." (PMID 38542192, 2024). "To explore the specific molecular mechanisms by which chronic circadian rhythm disruption causes osteoarthritis lesions in rat mandibular condylar cartilage, we examined the expression of matrix-degrading enzymes MMP13, ADAMTS4, and ADAMTS5." (PMID 39010104, 2024). "In summary, this study suggests that a loss of MIA/CD-RAP protects cartilage degradation during osteoarthritis by regulating MMP13." (PMID 36672165, 2023). "The levels of MMP13, a metalloproteinase involved in cartilage degradation and associated with osteoarthritis, were evaluated as well in chondroblastic progenitors in the presence of sera collected before and after the activity." (PMID 37685971, 2023). "IL6, TNFα, and MMP13, all of which are associated with osteoarthritis (OA) and compromised joint health, have been observed in MT-COMP joints." (PMID 37892235, 2023). "In the present study, chondrocytes stimulated with IL-1β exhibited downregulation of COL2A1 and upregulation of MMP13, Prg4, Sulf1, Adam10, and Fstl1, supporting that enhanced inflammation is a critical mechanism underlying the progression of osteoarthritis." (PMID 37525533, 2023). "Several studies affirmed that MMP13 is associated with articular cartilage destruction, proposing that a high MMP13 expression is associated with cartilage degradation during osteoarthritis." (PMID 36672165, 2023). "The up-regulation of metalloproteases, such as MMP-13, is a hallmark of osteoarthritis, where MMPs induce the degradation of extracellular matrix components." (PMID 35455454, 2022). "Of more clinical relevance, galactose-substitution blocked downstream functional features associated with osteoarthritis, including enhanced levels of MMP13 mRNA, MMP13 protein, and the degradative loss of proteoglycan from intact cartilage explants." (PMID 34302034, 2021). "Heterozygous HIF2α-deficient mice are resistant to osteoarthritis treatment, and exhibit reduced hypertrophic chondrocytes and MMP13 expression." (PMID 32079226, 2020). "The literature also supports a role for MMP13 in OA, where overexpression of MMP13 was shown to be sufficient to cause osteoarthritis in mice." (PMID 32853438, 2020). "In mice, ZIP8 overexpression increased MMP13 expression and osteoarthritis phenotypes, whereas ZIP8 deficiency markedly reduced the development of osteoarthritis." (PMID 32079226, 2020). "In contrast, MMP-13 is the only collagenase implicated in the degradation of collagenous matrices, and has a higher enzyme activity than other MMPs in osteoarthritis." (PMID 33213419, 2020). "Increasing ALK1/ALK5 ratios seem to be detrimental to cartilage, elevating e.g., MMP-13 expression, and to cause osteoarthritis-like symptoms in mice and men." (PMID 30959909, 2019). "Conditional deletion of Elf3 in mouse chondrocytes results in decreased IL-1β-mediated induction of Mmp13 and Nos2, and these mice undergo less cartilage loss in a model of osteoarthritis." (PMID 30200227, 2018).
osteoarthritis (continued). "In the context of osteoarthritis, both the collagenase MMP-13 and the aggrecanases ADAMTS-4 and ADAMTS-5 are susceptible to such ECM-mediated increase in TIMP-3 potency." (PMID 27582494, 2016). "It is worthy to note that MMP-13 is most notably associated with osteoarthritis and once its expression is elevated in the joint significant damage is imminent and the progression to joint destruction is rapid." (PMID 27478294, 2016). "As stated, a number of disease states involve overexpression of matrix metalloproteases, and there exist diseases in which mutations result in overexpression of MMP-13 and premature development of osteoarthritis." (PMID 27478294, 2016). "MMP-13 is involved in cartilage turnover and cartilage pathophysiology associated with osteoarthritis." (PMID 23356403, 2013). "S100A4 binds to RAGE, and has been implicated in upregulation of MMP-13 (Matrix Metalloproteinase 13) in osteoarthritis, which leads to tissue remodeling." (PMID 19292913, 2009). "Notably, dysregulated overexpression or activation of Mmp13 has been associated with the excessive bone tissue breakdown and contribution to the pathogenesis, e.g., in the case of osteoarthritis." (PMID 37701782, 2023). "In addition, sublytic MAC increased the multiple gene expression of chondrocytes implicated in osteoarthritis including MMPs, ADAMTSs, and inflammatory cytokines, and it was colocalized with MMP-13 and activated extracellular signal-regulated kinase (ERK)." (PMID 37483637, 2023). "Furthermore, in human articular chondrocytes, estradiol suppresses the expression of MMP1318; and an increase in MMP13 has been associated with the deleterious effects of estrogen deficiency in osteoarthritis and intravertebral disc degeneration." (PMID 35715555, 2022). "Hence, the MMP13 also plays a role in pathogenic conditions such as osteoarthritis by degrading cartilage ECM and inducing the chondrocyte hypertrophy, and the pathogenic roles of MMP13 are elucidated in the next chapter, ‘Hypertrophy in cartilage diseases’." (PMID 34452101, 2021). "Ddr1-/- mice were recently found to spontaneously develop osteoarthritis of the temporomandibular joint, suggesting that loss of Ddr1 and associated increases in Ddr2 may initiate MMP-13 upregulation, resulting in type 2-collagen degradation." (PMID 32330138, 2020). "Acetylated ligstroside aglycone significantly reduced the expression of pro-inflammatory genes including NOS2 and MMP13 at both RNA and protein levels; decreased nitric oxide release; and, importantly, reduced proteoglycan loss in human osteoarthritis cartilage explants." (PMID 32523668, 2020). "Excluding MMP13 mRNA from the study (which has already been linked to chondrocyte biological processes and osteoarthritis), studies with the top four dysregulated lncRNAs and mRNAs verified that qRT-PCR data for 53 specimens (34 OA and 19 normal specimens) were consistent with chip analysis." (PMID 31534838, 2019). "MMP13 is a hypertrophic marker and is believed to be involved in the transition phase of cells toward an osteochondral fate and has also been linked to osteoarthritis." (PMID 31242641, 2019). "MMP-13, a matrix metalloproteinase expressed in osteoarthritis cartilage and causes collagen degradation, was upregulated in σB treated group MMP2, was upregulated in both ARV and σB treated group, is known as the most potent type II collagen degrading protein and along with MMP-13." (PMID 29731966, 2018). "Moreover, increased MMP-13 expression has been implicated in osteoarthritis and rheumatoid arthritis." (PMID 29843672, 2018). "Given that MMP-1, MMP-3 and MMP-13 play pivotal roles in the cartilage matrix breakdown associated with both RA and osteoarthritis, the inhibitory effects of acacetin on MMPs indicates a potential role for acacetin in preventing cartilage degradation associated with RA." (PMID 25856795, 2015).
osteoarthritis (continued). "Spatially upregulated genes that overlap between SZ and HZ included an inhibitor of angiogenesis Adamts1, as well as matrix metalloproteinases Mmp9 and Mmp13, which are essential for endochondral bone formation but also implicated in the pathophysiology of osteoarthritis." (PMID 25068449, 2014). "MMP13 has been implicated in the cartilage damage of human osteoarthritis and rheumatoid arthritis and lack of MMP13 was shown to halt cartilage erosion in established osteoarthritis." (PMID 22253746, 2012). "In addition to the three miRNAs identified in our study, recent research has expanded our understanding of miRNAs in osteoarthritis (OA), highlighting their significant involvement in key OA-associated signaling pathways, including MMP13, STAT3, SMAD2/3, NOTCH3/Notch, and NF-κB." (PMID 39796139, 2024). "Although MMP-13 (collagenase 3) was first discovered in breast cancer, it remains a metalloproteinase with a major involvement in inflammatory diseases such as rheumatoid arthritis and osteoarthritis, where it is associated with the resorption and destruction of bones and cartilage." (PMID 35163727, 2022). "Research has confirmed that chondrocytes undergo ferroptosis under iron overload conditions, leading to increased MMP13 expression and decreased collagen II expression, which exacerbates osteoarthritis." (PMID 40429617, 2025). "Preceding studies demonstrated that MMP3 and MMP13 increased in chondrocytes to increase osteoarthritis progression by a ferroptosis promoter like ferric ammonium citrate." (PMID 40622464, 2025). "Previous studies have shown that RO 3306 suppresses osteoarthritis-related inflammation by reducing MMP-13 and IL-6 expression in chondrocytes and synovial fibroblasts." (PMID 41409278, 2025). "The authors showed that the mRNA expression of MMP-13 in chondrocytes from the Rb1 (10 μg/kg) administration group was about half of the control osteoarthritis group." (PMID 40507179, 2025). "In another study, Rb1 showed promising effects in inhibiting MMP-13 expression and promoting type II collagen expression through regulation of the Notch signaling pathway in osteoarthritis." (PMID 40507179, 2025). "PBMT improved OARSI scoring of osteoarthritis and suppressed IL-1β, caspase-3, and MMP-13 expression." (PMID 41009563, 2025). "TGF‐β can promote angiogenesis, infiltrate subchondral bone, exacerbate osteoarthritis progression, and increase the expression of terminal differentiation genes such as Mmp13, Runx2, and Col10a1." (PMID 40837199, 2025). "MMP-13, also known as collagenase-3, is a primary therapeutic target for osteoarthritis due to its critical role in cartilage degradation and disease progression." (PMID 40507179, 2025). "This led to the identification of 411 differentially expressed genes (DEGs) related to osteoarthritis, 2485 DEGs among subgroups, as well as 238 intersecting genes and 5 hub genes (MMP13, FAM26F, CHI3L1, TAC1, and CKS2)." (PMID 40216809, 2025). "HA injections have shown the ability to slow osteoarthritis progression by reducing glycosaminoglycan release and pro-inflammatory molecules, such as MMP-13, MMP-3, and IL-1β." (PMID 40943818, 2025). "CK treatment reduced IL-1β-induced iNOS, MMP-13, pJNK, pp38, and pErk expression and inhibited glycosaminoglycan release in chondrocytes from osteoarthritis patients." (PMID 40507179, 2025). "By inhibiting the mTORC1/S6K1 axis, DEPTOR considerably reduces the amount of MMP-13, which is consistent with the findings in the osteoarthritis model." (PMID 41249115, 2025). "CK also reduced cartilage degradation and normalized collagen II/MMP13 expression ratios in MCLT osteoarthritis mouse." (PMID 40507179, 2025). "These patches inhibited apoptosis of chondrocytes, MMP-13 activity, and NF-κB signaling pathway in osteoarthritis mice model induced by destabilization of the medial meniscus surgery." (PMID 40507179, 2025).
osteoarthritis (continued). "Although many researchers have investigated the function of TPX2 and MMP13 in a variety of cancers and diseases, their specific functions in lipopolysaccharide (LPS)-induced osteoarthritis remain largely unexplored." (PMID 38770093, 2024). "MMP-13 increased in the superficial zone of articular cartilage belonged to people with severe stages of osteoarthritis except of synovial membrane." (PMID 38396667, 2024). "AAVs expressing CRISPR-Cas9 were used to target NGF, IL-1β, and MMP13, which are commonly upregulated in osteoarthritis." (PMID 39598601, 2024). "Bone marrow mesenchymal stem cell therapy for osteoarthritis yields an effective outcome by downregulating MMP-13 and upregulating COL-II in articular cartilages." (PMID 38811966, 2024). "In the SASP, MMP13 has been identified as the most important factor contributing to the development of osteoarthritis." (PMID 38774874, 2024). "Within these proteinases, MMP-13 (collagenase-3) expression is acknowledged as having a role in bone resorption and cartilage destruction in conditions, such as rheumatoid arthritis and osteoarthritis." (PMID 38699090, 2024). "The active component harpagoside has been shown to suppress the expression of IL-6 and MMP13 in primary human osteoarthritis chondrocytes." (PMID 39519204, 2024). "In fact, the ability of EVs to protect against ECM hydrolysis by inhibiting MMP-13 expression has also sparked interest in their potential use in osteoarthritis therapies." (PMID 38790904, 2024). "It is well established that MMPs, especially MMP-13, also known as collagenase-3, play an important role in the progression of cartilage degradation in RA or osteoarthritis." (PMID 38543230, 2024). "Philllips found that blockade of MMP13 alleviated posttraumatic osteoarthritis through inhibition of immune restructuring, angiogenesis, innate immune response, and proteolysis." (PMID 38385005, 2024). "MMP-13 proves valuable in the diagnosis and assessment of disease severity, as well as in the prediction of osteoarthritis development." (PMID 38396667, 2024). "The study identifies MMP-13 as a potential key player in the development and progression of osteoarthritis, with increased concentrations in synovial fluid indicating both local and systemic inflammation." (PMID 38396667, 2024). "Articular chondrocytes from MT-COMP/CHOP−/− mice displayed higher IL-10 and lower TNFα levels, which influenced key molecules such as SIRT1 and MMP-13, both critical to joint health and osteoarthritis progression." (PMID 39795874, 2024). "Matrix metalloproteinase 13 (MMP13) is an important enzyme involved in arthrodial cartilage degeneration, and cartilage ECM degeneration is a hallmark of osteoarthritis." (PMID 36982438, 2023). "According to Galasso and colleagues’ literature review, MMP-1, MMP-3, MMP-7, MMP-8, and MMP-13 are involved in osteoarthritis pathogenesis, but the role of gelatinases (MMP-2 and MMP-9) is not negligible." (PMID 36830637, 2023). "MMP-13 is considered the pivotal proteinase that marks osteoarthritis development and progression of osteoarthritis." (PMID 37685971, 2023). "The hybrid CAP-Exo successfully suppressed the production of MMP-13 in chondrocytes, penetrated the deep region of the cartilage matrix in osteoarthritis rats, and attenuated the hydrolytic breakdown of the extracellular matrix proteins in the cartilage." (PMID 37842166, 2023). "Circ_0000423/miRNA-27b-3p/MMP-13 axis regulates cartilage ECM synthesis in osteoarthritis, and exosome-transported circRNA_0001236 enhances chondrogenesis and inhibits cartilage degeneration via miR-3677-3p/Sox9 axis." (PMID 36980895, 2023). "Piperine has an anti-inflammatory effect and can inhibit the expression levels of inflammatory factors (iNOS, COX-2) and degenerative factors (MMP3, MMP13) in IL-1β-stimulated osteoarthritic chondrocytes, thereby treating osteoarthritis." (PMID 37525208, 2023).